IGF2 (insulin like growth factor 2)
Diseases named in the same sentence as IGF2 in open-access papers (continued):
Sharing a sentence is not in itself a finding about the gene and the disease.
insulinoma (23 papers, 2009 to 2025). "Finally, some forms of insulinomas, endocrine pancreatic tumours that lead to severe forms of hyperinsulinemic hypoglycaemia, associated hypermethylation at the IGF2 differentially methylated region 2 (IGF2-DMR2), with IGF2 loss-of-imprinting and overexpression." (PMID 33833312, 2021). "Finally, IGF2 overexpression was also detected in Men1-mutated mouse insulinoma." (PMID 33101198, 2020). "IGF2 is normally expressed only during development but is upregulated in RIP1-Tag2 insulinomas (the source of βTC cells), where it promotes proliferation and protects against apoptosis." (PMID 34359576, 2021). "This would provide an opportunity for other transcriptional regulators to control the expression from the INS/IGF2 locus in insulinomas." (PMID 33060578, 2020). "Rat primary β-cells and mouse insulinomas showed an adhesion remodeling during GSIS resulting from autocrine insulin/IGF2 and AKT1 signaling." (PMID 32934005, 2020). "Glutamine can also stimulate biosynthesis and secretion of IGF2 in mouse insulinoma cells, which regulate beta-cell mass and function in an autocrine manner." (PMID 33101198, 2020). "An artificial endocrine pancreas has been reported as beneficial for patients with insulinoma as it maintains stable glycemic levels, although scarcely described with insulin-like growth factor 2-releasing tumor." (PMID 32025979, 2019). "Different in vitro and in vivo animal model studies have brought evidence of the involvement of insulin-like growth factor 2 (IGF2) in insulinoma tumorigenesis." (PMID 29853883, 2018). "Moreover, in a mouse model of multistage carcinogenesis induced by the SV40 large T antigen in pancreatic beta-cells, IGF2 was increased and contributed to insulinoma development." (PMID 33101198, 2020). "This suggests that NFATC1 may serve as an alternate driver of INS/IGF2 expression in insulinomas, possibly facilitated by looping from the SYT8/TNNI2 locus." (PMID 33060578, 2020). "IGF2 was upregulated in several insulinomas, but mostly unchanged compared to beta cells." (PMID 28974674, 2017). "This possibility would be reminiscent to some human pancreatic tumors like insulinomas where Igf2 DMR2 is hypermethylated while the H19 ICR is monoallelically methylated and where Igf2 becomes also expressed from the unmethylated maternal allele (loss of imprinting)." (PMID 22662250, 2012). "These latter observations suggest that NFaT transcription factors may respond to non-islet-specific signals that participate in modifying chromatin structure in the 11p15.5-p15.4 target sub-region, thereby affecting the expression pattern of the INS/IGF2 locus in insulinomas." (PMID 33060578, 2020). "That study suggested widespread methylation abnormalities in this region in insulinomas, that likely affected the expression of key genes in the INS/IGF2 locus, the CDNK1C, and others." (PMID 33060578, 2020). "Only hypermethylated PDX1 and NKX3-1 binding sites in insulinomas mapped to islet-specific enhancers (7/14), and the majority of these (4/7) were near the INS/IGF2 locus." (PMID 33060578, 2020). "Furthermore, the extract upregulated PDX-1 gene expression, contributing to increased gene transcription of insulin-like growth factor 2 (IGF-2) and insulin in INS-1 cells (rat insulinoma cell line, a β-cell line)." (PMID 34335803, 2021). "Its efficacy has been reported in patients with insulinoma, although its benefits in patients with NICTH with IGF2 elevation remain unclear." (PMID 32025979, 2019). "Both MutL homolog 1 (MLH1) and Insulin-like growth factor 2 (IGF2) are frequently methylated in insulinomas, but not in other pNETs." (PMID 27418145, 2016). "Parenthetically, the two ICRs in this region, the H19/IGF2 ICR (chr11: 2,018,812–2,024,740) and KvDMR1 (chr11: 2,719,948–2,722-259), each displayed approximately equal percent methylation in beta cells (49.5% and 41.9%, respectively) and insulinomas (47.9% and 36.5%, respectively)." (PMID 33060578, 2020).
adrenocortical carcinomas (22 papers, 2012 to 2025). "Reciprocal regulation of IGF-2 and H19 expression is seen in adrenocortical carcinoma, where H19 suppression by promoter methylation is associated with increased IGF-2 expression and cell proliferation." (PMID 35597813, 2022). "Our findings demonstrate that metformin inhibits proliferation in the adrenocortical cancer cell model H295R in association with a decreased expression of the IGF2/IGF-1R system." (PMID 27391065, 2016). "Overexpression of insulin growth factor 2 (IGF2) is a hallmark of adrenocortical carcinomas and pheochromocytomas." (PMID 26400872, 2015). "This seems particularly relevant in light of the recent finding that mTOR pathway is activated and involved in growth stimulation of paediatric adrenocortical carcinomas, tumour entities that are also associated with IGF2 overexpression." (PMID 22952916, 2012). "Both genetic and proteomic data consistently reveal the frequent overexpression of the insulin-like growth factor 2 (IGF2)-H19 locus in adrenocortical carcinomas (ACCs)." (PMID 38505747, 2024). "The insulin-like growth factor 2 (IGF2) promotes cell growth by overactivating the IGF system in an autocrine loop in adrenocortical carcinomas (ACCs)." (PMID 38068896, 2023). "Subsets of adult cancers also overexpress IGF2, including 20% of hepatocarcinoma, 40% of colon carcinoma, 90% of liposarcoma, and also adrenocortical carcinoma." (PMID 25089899, 2014). "The role of IGF2 in the progression of adrenocortical carcinoma (ACC) has been debated for almost two decades." (PMID 25089899, 2014). "In malignant adrenal cortical tumours, the second most frequent alteration after IGF2 overexpression is constitutive activation of β-catenin." (PMID 22952916, 2012). "Altered DNA methylation of the H19 promoter has been shown to be involved in the abnormal expression of both H19 and IGF-2 genes in adrenocortical carcinomas." (PMID 24832650, 2012). "Using mTOR inhibitors could weaken the promoting effect of IGF on the proliferation and viability of tumor cells, while combining IGF2 inhibitors could provide a better curative effect on patients with adrenocortical carcinoma." (PMID 33582655, 2021). "Adrenocortical carcinoma cells (H295R) express large amounts of IGF2." (PMID 25089899, 2014). "The growth factor IGF2 is overexpressed in almost all adrenal cortical carcinomas, suggesting that it may play a role in malignant adrenal tumour formation in patients." (PMID 22952916, 2012). "Additionally, in malignant neoplasms, hyperinsulinemia may potentiate the proliferative effect of IGF-2, which is overexpressed in 90% of adrenocortical carcinomas, through the binding of insulin receptor A (IR-A), IGF-1 receptor (IGF-1R) and hybrid receptor IR-A/IGF-1R." (PMID 39199391, 2024). "Genetic alterations at the 11p15 chromosomal locus result in an overexpression of IGF-2 in adrenal cortex cells and are fairly specific to both sporadic and syndromic adrenocortical carcinomas but not adenomas." (PMID 25889798, 2015). "IGF2 protein and mRNA were shown to be significantly increased in metastatic PPGL, which is consistent with other studies investigating the relationship between IGF2, miR-483-5p, and adrenocortical carcinoma, where miR-483-5p is also overexpressed in comparison to benign adrenocortical adenomas." (PMID 33810219, 2021). "In addition, IGF2 was demonstrated to influence adrenocortical cancer cell proliferation, metabolism, and viability, but not the cell invasion." (PMID 31378849, 2019). "Moreover, IGF2 was demonstrated to influence adrenocortical cancer cell proliferation, metabolism, and viability, but not cell invasiveness." (PMID 31378849, 2019).
Hyperinsulinemia (22 papers, 2011 to 2025). An increased concentration of insulin in the blood. "Accordingly, constitutive IR autophosphorylation detectable in human BCs is likely explained by exposure to hyperinsulinemia and/or to local IGF2 secretion and is associated with poor patient survival." (PMID 31480557, 2019). "Notably, in vitro evidence has shown that insulin resistance and hyperinsulinemia contribute to a high risk of PCa by altering the biological function of IGF-1 or IGF-2." (PMID 38243202, 2024). "Meanwhile, in vitro culture experiments confirmed the effect of insulin stimulation on IGF2/H19 in HepG2 cells, providing a potential explanation for intrauterine hyperinsulinemia directly affecting IGF2/H19 and subsequent impaired glucose metabolism." (PMID 35432202, 2022). "Hyperinsulinemia increases the bioavailability of insulin-like growth factor 2 (IGF2) through its effect on growth hormone in liver." (PMID 30200454, 2018). "Hyperinsulinemia, present in insulin resistant conditions, may worsen the prognosis of TC likely by potentiating IR-A/IGF2-dependent mitogenic functions." (PMID 33114365, 2020). "These IR-A-dependent metabolic effects are responsive to both IGF2 and insulin and might play a role in BC progression in obese and/or diabetic patients with hyperinsulinemia." (PMID 31480557, 2019). "The hyperinsulinemia, associated with other growth factors like IGF-1 and IGF-2, could be responsible for hypoglycemic accidents of newborns." (PMID 30539027, 2018). "In conclusion, our study demonstrated that intrauterine hyperinsulinemia increased hepatic FoxO1 levels and contributed to the upregulation of DNMT3A, subsequently inducing the downregulation of IGF2/H19 expression in the liver of GDM-F1 mice." (PMID 35432202, 2022). "Our results demonstrated that the intrauterine hyperinsulinemia environment has increased hepatic FoxO1 levels and subsequently increased expression of DNMT3A and epigenetic alterations on IGF2/H19 DMRs." (PMID 35432202, 2022). "Furthermore, another concept to be highlighted is that hyperinsulinemia, present in insulin-resistant conditions, may favor IR-A/IGF-2 loop activation, thereby potentiating IR-A-dependent mitogenic functions via MAPK/PI3-K/mTOR signaling activation, and worsening the prognosis of TC." (PMID 30513575, 2018). "As hyperinsulinemia can also affect the expression level of IGFI and IGFII, we used semi-quantitative PCR to compare the levels of both Igf1 and Igf2 mRNA in MKR+/+ and control mice." (PMID 22226054, 2012). "Hyperinsulinemia increases insulin-like growth factor (IGF)-1 production in the liver, and decreases the levels of IGF binding proteins, leading to increased bioavailable IGF-1 and IGF-2 levels." (PMID 35802721, 2022). "Yet, hyperinsulinemia by increasing the bioavailability of IGF-1 and IGF-2 may favor tumor progression and the activation of IGF-1R, IR/IGF-1R hybrids, IR-A, and their interaction with other molecular partners." (PMID 30513575, 2018).
liver cancer (22 papers, 2005 to 2025). An epithelial or non-epithelial malignant neoplasm that arises from the liver. "In vitro assays, SLC27A5 holds promise as a potential prognostic marker for liver cancer and IGF2 has been linked to unfavourable clinical outcomes." (PMID 39628446, 2024). "MiR-483-3p is located within the insulin growth factor (IGF2) locus at chromosome 11p15.5 and implicated in various human cancers including colon, breast, liver cancers and squamous cell carcinomas." (PMID 26801758, 2016). "Particularly, several key genes, such as SLC27A5, IGF2, EFNA3, DCAF4L2, and SPP1, have been demonstrated to be associated with liver cancer." (PMID 39628446, 2024). "For example, hsa_circRNA_100084 can act as a sponge for hsa-miR-23a-5p to promote the expression of IGF2 in liver cancer cells, thereby promoting their proliferation, migration, and invasion." (PMID 37953794, 2023). "Deletion of insulin‐like growth factor 2 (IGF2) prevents liver cancer in the serine‐arginine rich splicing factor 3 (SRSF3) knockout mouse model by restoring DNA repair enzymes and preventing DNA damage." (PMID 35615981, 2022). "IGF2 mRNA-binding proteins (IGF2BPs) can specifically bind to the lncRNA HULC (Highly Up-regulated in Liver Cancer) HULC, thereby controlling its expression." (PMID 33228611, 2020). "We first evidenced a concomitant and marked overexpression of IGF2 and miR-483-3p in liver cancer cell lines." (PMID 31320614, 2019). "Clusters 1, 2, 3, 5, and 6 represented genes that were highly expressed in stages of embryonic development, but were expressed at low levels in adult livers, including oncofetal genes Afp, Gpc3, Sall4 (cluster 2), H19 (Cluster 3) and Igf2 (Cluster 5), which are re-expressed in liver cancer." (PMID 38225233, 2024). "As shown by the study, the role of the Menin/MLL complex provides another mechanism to overcome the imprinting-promoting status of H3K27 methylation on the maternal allele, ultimately allowing for biallelic IGF2 expression and potentiation of the IGF-II oncogenic signal in liver cancer." (PMID 37371750, 2023). "The results indicate that IGF2 overexpression in conjunction with reduced SRSF3 splicing activity could be a major cause of DNA damage and driver of liver cancer." (PMID 35615981, 2022). "This promoter switching may be important in HCC as altering the methylation status of P4 to reduce IGF2 expression enhances survival in a Hep3B liver cancer model and reducing IGF2 levels by siRNA reduces c‐Myc and N‐Ras signaling in HCC." (PMID 35615981, 2022). "Notably, experimental rescue of miR-493-5p promoted an anti-cancer response by negatively regulating the expression of insulin-like growth factor 2 (IGF2)-derived oncomir miR-483-3p in liver cancer cell lines exhibiting IGF2 LOI." (PMID 31320614, 2019). "In summary, this study describes an unknown miRNA-dependent regulatory mechanism between two distinct imprinted loci and a possible therapeutic window for liver cancer patients exhibiting IGF2-miR-483 LOI and amplification." (PMID 31320614, 2019). "To clarify the impact of the miR-493-5p-IGF2 axis in liver cancer cells, we tested whether IGF2 experimental silencing could mimic the tumor-suppressor activity mediated by miR-493-5p." (PMID 31320614, 2019). "IGF2 overexpression and SRSF3 loss could thus be a major cause of DNA damage and liver cancer." (PMID 35615981, 2022). "Our research described the regulatory role of IGF2 in the TME from a new perspective, targeting the IGF2/IGF2R/MAPK axis to potentially suppress the CCA in primary liver cancer." (PMID 39674501, 2025).
liver cancer (continued). "HBx upregulates IGF‐1R expression and increases IGF‐2 transcription by interacting with the Sp1 binding site on IGF‐2 promoter, which collectively lead to IGF‐2 overexpression and aberrant IGF signaling, accelerating liver cancer progression." (PMID 40060195, 2025). "In this study, the author proved that AQP9 mediated by insulin-like growth factor 2 (IGF2), inhibited liver cancer stem cell stemness through ROS/β-catenin/FOXO3a." (PMID 35972604, 2022). "TGF-β, together with the chromatin insulator CCCTC-binding factor (CTCF), epigenetically and transcriptionally regulate tumor promoter genes, including IGF2 and TERT, in TGF-β–defective mice and in human liver cancers." (PMID 33457451, 2020). "IGF2BPs promote the synthesis of growth factors like IGF2 and consistently enhances ERK1/2-activity in liver cancer cells." (PMID 30371874, 2019). "Interestingly, in hepatocarcinoma cells, miR-493-5p displayed anti-tumor activity by inhibiting the IGF2-derived intronic miR-483-3p, the expression of which correlates with IGF2-LOI in liver cancer cells." (PMID 37371750, 2023).
adenoma (18 papers, 2005 to 2025). A neoplasm arising from the epithelium. "We were unable to evaluate the association between IGF2 methylation in PBLs and the risk of developing adenomas." (PMID 37213278, 2023). "Moreover, MMR-deficient adenomas with a high grade of dysplasia revealed hypermethylation in four other genes, IGF2, CRABP1, NEUROG1, and CDKN2A." (PMID 34201893, 2021). "The xenografted mice were treated with IGF2R/CI-M6PR, an inhibitor of IGF2, and showed a decrease in Igf2-dependent adenoma phenotype." (PMID 38542291, 2024). "For example, using these datasets we found significant associations between IGF2 hypermethylation in tissues and an increased risk of CRC or adenomas." (PMID 37213278, 2023). "In the first pathway, adenoma formation occurs in an MMR-proficient background, and carcinogenesis is characterized by APC and/or KRAS mutation and IGF2, NEUROG1, CDK2A, and/or CRABP1 hypermethylation." (PMID 34201893, 2021). "LS patients with CRC show a higher amount of hypermethylated IGF2 in adenoma and adenocarcinoma tissue compared to normal colon mucosa." (PMID 34201893, 2021). "A recent study also showed that multiple CIMP marker genes (including IGF2) showed significantly increased methylation in DNA mismatch repair proficient (MMR-P) adenomas of Lynch syndrome patients." (PMID 31623387, 2019). "According to some of the researchers, IGF2 is the most differentially expressed gene between carcinoma and adenoma lesions." (PMID 31623387, 2019). "DNA was available for eight such adenomas, and 3/8, 4/8, 6/8, and 2/8 revealed hypermethylation of IGF2, NEUROG1, SFRP1, and SFRP2, respectively." (PMID 26203307, 2015). "IGF2, p27, cyclin D1, and Ki-67 were the markers for which the percentage of stained area was significantly higher in carcinoma samples than in adenoma samples." (PMID 23925558, 2013). "IGF2 staining was positive in most carcinomas, in contrast to adenomas." (PMID 39890749, 2025). "We can hypothesize that IRA overexpression may have a stronger impact in carcinomas, that also overexpress its ligand IGF2, than in adenomas." (PMID 40038716, 2025). "Notably, the difference was significant already in adenomas with low-grade dysplasia (89 % vs. 21 %, p < 0.001, for IGF2 and 56 % vs. 8 %, p < 0.001, for NEUROG1)." (PMID 26203307, 2015). "Ki-67 and p27 were the markers that exhibited the highest discriminative power for differential diagnosis between carcinomas and all type of adenomas, while IGF2 and StAR were only found to be useful for differentiating between carcinomas and ACAn and between carcinomas and ACAc respectively." (PMID 23925558, 2013). "Conversely, the reduction of Igf2 expression resulting from deletion of the transcriptionally active paternal allele or from the use of a soluble form of the scavenger IGF2R receptor, is associated with reduced number of adenomas and decreased malignant progression." (PMID 22952916, 2012). "Moreover, Maki-Nevala and colleagues found higher methylation levels in four CIMP marker genes, namely NEUROG1, CDKN2A, IGF2, and CRABP1, in MMR-proficient adenomas compared to normal mucosa." (PMID 34201893, 2021). "Among the seven upregulated genes the expression levels of which were over five times higher than those in the matched normal tissues, the expression levels of IGF-2, E1AF, iNOS, nm23, Smad4, and TIMP-1 genes were significantly higher in the early invasive carcinoma group than in the adenoma group." (PMID 15785755, 2005). "Adrenal tumour patients only show IGF2 overexpression in carcinomas but not adenomas." (PMID 22952916, 2012). "The prospective LS series revealed increased methylation in adenomas and carcinomas vs. normal colonic mucosa for the CIMP markers IGF2, NEUROG1, and CRABP1 (p values mostly non-significant due to small numbers of specimens)." (PMID 26203307, 2015).